TG (thyroglobulin)
Diseases named in the same sentence as TG in open-access papers (continued):
Sharing a sentence is not in itself a finding about the gene and the disease.
thyroid cancer (301 papers, 1985 to 2026). "Fine needle aspiration cytology (FNAC) and thyroglobulin (Tg) are the primary diagnostic modalities employed for assessing metastatic lymph nodes (LNs) in thyroid cancer." (PMID 38828358, 2024). "In this study, we aim to explore the correlation between these critical biological markers—BRAF V600E mutation, thyroglobulin, and calcitonin—and the prognosis of thyroid cancer." (PMID 39767732, 2024). "We illustrated that anti-TG antibodies are associated with a 5.7-fold increase in the risk of thyroid cancer in Bethesda III and IV nodules." (PMID 39886714, 2024). "This study examines the relationship between biological markers—BRAF V600E mutation, thyroglobulin (Tg), and calcitonin—and thyroid cancer prognosis." (PMID 39767732, 2024). "Thyroglobulin (Tg), a precursor protein for thyroid hormones that are crucial for human growth and metabolic regulation, is considered to have a good diagnostic performance in LN metastasis of thyroid cancers." (PMID 38828358, 2024). "Thyroglobulin is a tissue specific‐protein produced by thyroid follicular cells, it is a thyroid carcinoma marker used in diagnostic pathology." (PMID 38817707, 2024). "In spite of detecting thyroglobulin in saliva, it was impossible to use this as a marker to assess the risk of thyroid cancer or Graves’ disease repercussions." (PMID 36981758, 2023). "The use of thyroglobulin testing in diagnostic methods has yielded substantial advancements in detecting recurring thyroid cancer, augmenting patient care, and overall results." (PMID 38111456, 2023). "High-frequency ultrasound combined with the detection of serum high mobility group box (HMGB-1), sIL-2R, and thyroglobulin antibody level (TgAb) has diagnostic power in thyroid cancer (sensitivity: 98.0% and specificity: 95.0%)." (PMID 36092957, 2022). "TG Ab interferes with the serum thyroglobulin immunometric assay (IMA) measurement causing TG underestimation with the risk of missing detection of persistent or recurrent thyroid cancer." (PMID 34512731, 2021). "Associations between autoimmune thyroiditis and thyroid cancer have been documented in studies where thyroid autoimmunity was assessed by measuring thyroglobulin antibody and thyroid peroxidase antibody." (PMID 34032581, 2021). "Thyroglobulin expression assessed by immunohistochemistry has been used for its diagnostic value in differentiating thyroid cancer tissue for decades." (PMID 34298840, 2021). "Because of the strong association between elevated serum thyroglobulin and thyroid cancer, this patient will receive comprehensive endocrinology evaluation." (PMID 34631064, 2021). "Next, we reviewed the utility of cfRNA measurement in a thyroid cancer patient with innate production of thyroglobulin antibodies (TG Ab) due to underlying autoimmune lymphocytic thyroiditis." (PMID 34512731, 2021). "In a thyroid cancer patient with such mutation, pioglitazone for 6 months shrank an acetabulum metastatic lesion (6 to 3.9 cm) and lowered thyroglobulin by 97%." (PMID 31614690, 2019). "Tg (thyroglobulin) is elevated in the patients with thyroid nodules and adenomas, which is considered as a risk factor of thyroid cancers." (PMID 29495605, 2018). "The undifferentiated thyroid cancer phenotype of ATC is characterized by a loss of expression of differentiation markers such as thyroglobulin and the sodium-iodide symporter (NIS) as well as an increased proliferative rate." (PMID 29383121, 2017). "Serum VAP-1 level negatively associated with serum thyroglobulin concentration in thyroid cancer patients and has a good capability in the diagnosis of thyroid cancer." (PMID 27446209, 2016). "In recent years, two diagnostic methods (US-guided FNAC and detection of thyroglobulin on FNA (FNA-Tg)) are often used to diagnose suspicious CLN metastases from thyroid cancer." (PMID 26649004, 2015).
thyroid cancer (continued). "Thyroglobulin gene mutation is a rare cause of congenital hypothyroidism, but thyroglobulin gene mutations are thought to be associated with thyroid cancer development." (PMID 22934199, 2012). "Loss of TTF-1 causes differentiated or poorly differentiated thyroid cancer to lose the ability to absorb, concentrate radioactive iodine, and produce thyroglobulin during progression.In previous studies, it expressed nearly 100% of PTC and follicular thyroid carcinomas." (PMID 39882267, 2024). "The diagnosis of thyroid carcinoma at an older age, accompanied by elevated initial thyroglobulin antibody levels and a notable familial predisposition, may raise concerns about the potential occurrence of synchronous or metachronous tumors." (PMID 38894738, 2024). "The diagnosis of thyroid carcinoma at an older age, accompanied by elevated initial thyroglobulin antibody levels and a notable familial predisposition, may raise concerns about the potential occurrence of synchronous or metachronous neoplastic manifestations." (PMID 38894738, 2024). "The BRAF status and stimulated thyroglobulin levels at ablation time improve the ATA risk stratification of differentiated thyroid cancer; therefore, even A-hTg could be included in risk classification factors." (PMID 31093278, 2019). "A panel of CEC quantification with serum thyroglobulin testing could be a valuable diagnostic marker for monitoring of thyroid cancer patients." (PMID 30595827, 2018). "The sensitive detection of circulating tumour cells in patients with differentiated thyroid cancer may precede the detection of relapse by other diagnostic studies – such as serum thyroglobulin – and thus may have important therapeutic and prognostic implications." (PMID 10817499, 2000). "Among the variables included, thyroglobulin (Tg) and lymph node metastasis count were identified as the most influential predictors, consistent with their established roles in thyroid cancer progression." (PMID 41393114, 2025). "The utility of thyroglobulin (Tg) in the follow-up of patients with differentiated thyroid cancer has been well-documented." (PMID 39150986, 2025). "The issue surrounding interference between TgAb and thyroglobulin continues to be classified as “indeterminate response to treatment” when clinically evaluating patients with thyroid cancer." (PMID 40423684, 2025). "For example, after a thyroidectomy for thyroid cancer, thyroglobulin, a precursor to thyroid hormones, is regularly monitored to ensure it remains below the limit of detection." (PMID 39974195, 2025). "Serum thyroglobulin, a glycoprotein produced exclusively by thyroid follicular cells, serve as a key tumor marker for differentiated thyroid carcinoma." (PMID 40746588, 2025). "Unlike traditional methods that focus on tumor imaging and biomarker measurements (such as thyroid-cancer-specific thyroglobulin or calcitonin), metabolomics can monitor the treatment response using the analysis of metabolic reprogramming." (PMID 40149351, 2025). "The endocrinologist diagnosed non-toxic multinodular goiter and ordered anti-thyroid peroxidase (ATPO) and anti-thyroglobulin (anti-TG) tests to screen for thyroid carcinoma." (PMID 40225451, 2025). "We used the National Health and Nutrition Examination Survey (NHANES) data for heavy metal levels and the thyroglobulin antibody (TgAb) as a thyroid cancer marker." (PMID 39330560, 2024). "Monitoring thyroglobulin levels is crucial in treating thyroid cancer patients, particularly those with differentiated thyroid cancers such as PTC and FTC." (PMID 39767732, 2024). "Post-operative surveillance for thyroid cancer is heavily dependent on serum thyroglobulin (Tg) levels." (PMID 38291522, 2024). "An integral aspect of post-treatment surveillance in thyroid cancer management is monitoring thyroglobulin (Tg) levels, a biomarker typically indicative of residual or recurrent disease." (PMID 39040438, 2024).
thyroid cancer (continued). "Serum tumor marker thyroglobulin is useful as a prognostic marker for differentiated thyroid cancer after its removal." (PMID 38791947, 2024). "The Kaplan–Meier survival analysis highlights the prognostic impact of preoperative thyroglobulin and calcitonin levels on five-year survival rates and median survival across histological thyroid cancer subtypes." (PMID 39767732, 2024). "Biomarkers like thyroglobulin (Tg) and thyroglobulin antibodies (TgAb) are available for disease monitoring in specific thyroid cancer subtypes, but their effectiveness is limited." (PMID 39061714, 2024). "This study highlights the significant prognostic value of thyroglobulin and calcitonin in thyroid cancer." (PMID 39767732, 2024). "For example, serum thyroglobulin measurements via LC–MS/MS are resistant to interference by anti-thyroglobulin antibodies that hinder its quantification by commercially available immunoassays in approximately 25% of differentiated thyroid cancer patients." (PMID 38287260, 2024). "Of the participants with thyroid cancer, 75% showed a reduction in thyroglobulin levels, and 60% of all the participants showed a decrease in neutrophil-to-lymphocyte ratio during treatment." (PMID 39139285, 2024). "On the contrary, if the thyroglobulin level is significantly elevated after a total thyroidectomy, there is an increased likelihood of persistent thyroid cancer." (PMID 39272954, 2024). "75% of the patients with thyroid cancer showed a reduction in thyroglobulin levels, and 60% of patients showed a decrease in NLR during treatment." (PMID 39139285, 2024). "All four patients with thyroid cancer had thyroglobulin levels tested at the beginning and end of follow-up." (PMID 39139285, 2024). "The thyroglobulin (Tg) is a well-established serum biomarker used in the clinical management of patients after they have undergone treatment for thyroid carcinoma." (PMID 38389054, 2024). "Serum markers include thyroglobulin (Tg) and anti-thyroglobulin antibodies (TgAb) for follicular cell-derived thyroid carcinoma, and calcitonin and CEA for MTC." (PMID 39325263, 2024). "•Thyroglobulin (TG) dosage can enhance the accuracy of detecting well-differentiated thyroid carcinomas." (PMID 39612781, 2024). "Biomarkers such as thyroglobulin (TG), calcitonin, and BRAF V600E mutations play distinct roles in diagnosing and prognosis thyroid carcinoma subtypes." (PMID 39767732, 2024). "Thyroglobulin (TG) dosage enhances the accuracy of detecting well-differentiated thyroid carcinomas." (PMID 39612781, 2024). "The assessment of serum thyroglobulin, frequently combined with imaging examinations, assists in monitoring individuals with thyroid cancer following their therapy." (PMID 38111456, 2023). "This analysis revealed that seven of the novel identified variants were located in genes previously associated with thyroid cancer: MSH6, FOXM1, EPCAM, HOOK3, BMP1, TG and NTRK1." (PMID 37175550, 2023). "An optical fiber nano-optrode based on LPG in reflection configuration was used to detect the human Thyroglobulin (TG), a protein marker of differentiated thyroid cancer." (PMID 37504073, 2023). "It is the main precursor to thyroid hormones, and thyroglobulin levels in blood are used as a tumor marker for thyroid cancer." (PMID 37853181, 2023). "The introduction of thyroglobulin tests during the 1970s provided a significant means of monitoring individuals with thyroid cancer following their therapy." (PMID 38111456, 2023). "Serum thyroglobulin, a tumor marker in thyroid cancer, was elevated and stabilized during the treatment period." (PMID 35510953, 2022). "Well differentiated thyroid cancers almost universally express the markers thyroid transcription factor-1 (TTF-1), PAX8, thyroglobulin and B-catenin; however, loss of expression of these proteins is often characteristic of ATC." (PMID 35193694, 2022).
thyroid cancer (continued). "The present study aimed to detect the role of new markers, including galectin-3 (Gal-3) and thyroglobulin (TG), in the prognosis and staging of thyroid cancer." (PMID 35203561, 2022). "American Thyroid Association guidelines recommend to follow athyreotic differentiated thyroid cancer patients with measurement of serum thyroglobulin and thyroglobulin antibody as tumor markers." (PMID 36601182, 2022). "Both preoperative US and serum thyroglobulin level provide a specific value when evaluating the N staging of thyroid cancer, and the combined method is more valuable in the diagnosis of LNM than US alone." (PMID 36429049, 2022). "A higher concentration of urine exosomal thyroglobulin protein was found in late-stage patients with thyroid carcinoma compared to those with early stage in our previous study." (PMID 36672532, 2022). "Thyroglobulin is the most specific and generally sensitive for well-differentiated follicular-derived thyroid carcinoma; however, some primary thyroid neoplasms have weak or absent expression of the marker." (PMID 35328664, 2022). "Our previous study showed that UEx thyroglobulin concentration correlated with severity of thyroid carcinoma progression, therefore had potential as a biomarker." (PMID 36672532, 2022). "The specific expression of thyroid cancer-related proteins (cytokeratin, CK; thyroglobulin, Tg and thyroid transforming factor-1, TTF-1) were detected by the immunohistochemical analysis." (PMID 33578538, 2021). "Thyroid cancer surveillance for recurrence is performed using ultrasound scan of neck, cross-sectional imaging in some patients, along with serum thyroglobulin (TG) to monitor disease burden in response to treatment." (PMID 34512731, 2021). "Thyroglobulin in serum also plays a key role in the surveillance of differentiated patients with thyroid cancer." (PMID 34032581, 2021). "Differentiated thyroid cancer produces thyroglobulin (Tg) that is used as a specific and sensitive serum marker of the disease." (PMID 34638232, 2021). "In the management of patients with differentiated thyroid cancer, thyroglobulin (Tg) is used as a tumor marker to predict residual disease." (PMID 33467717, 2021). "Most studies have shown a significant relationship between thyroid cancer and positive antibodies to thyroglobulin and histological proof of AT." (PMID 33801319, 2021). "Thyroid-specific genes, including thyroid-stimulating hormone receptor (TSHR), sodium/iodide symporter (NIS), thyroperoxidase (TPO) and thyroglobulin (TG), are downregulated in thyroid cancer." (PMID 34155535, 2021). "Lastly, patients with poorly differentiated thyroid cancers lose the ability to produce thyroglobulin, making the measurement of thyroglobulin an unreliable reflection of tumour burden in these patients." (PMID 34512731, 2021). "Although PDTC loses the component of well-differentiated thyroid carcinoma, it produces thyroglobulin, contains colloids, and retains the ability to respond to radioactive iodine." (PMID 34830540, 2021). "The significant and novel finding in the present study is that in comparison with serum thyroglobulin, urinary exosomal thyroglobulin (U-Ex Tg) can be an important pro-inflammatory predictor and biomarker of thyroid cancer recurrence." (PMID 32612576, 2020). "Serum thyroglobulin is a pivotal biomarker for detecting possible residual tumors or recurrence of thyroid cancer." (PMID 32612576, 2020). "For patients receiving total thyroidectomy and/or ablation with radioactive iodine, the increasing tendency of U-Ex Tg revealed that it can be used as a substitute for undetectable serum thyroglobulin in predicting the recurrence of thyroid cancer." (PMID 32612576, 2020). "The second case involved an 84-year-old man with a mediastinal tumor and suspected thyroid cancer because of high thyroglobulin levels in blood." (PMID 32328315, 2020).
thyroid cancer (continued). "The presence of CTCs in thyroid cancer was demonstrated by staining for thyroid-specific/abundant proteins (thyroglobulin and NIS) expressed by circulating blood cells." (PMID 30781659, 2019). "ATC lacks most markers seen in thyroid cancer such as thyroglobulin, TTF1, NIS, and TSHR, except PAX8 that can be present consistently in squamous variant ATC but in only 50% of ATC with spindle cell features." (PMID 31835496, 2019). "Possible indicators of success for robotic thyroidectomy include postoperative serum thyroglobulin levels, remnant thyroid tissue on ultrasound, and recurrence of thyroid cancer." (PMID 30909509, 2019). "In previous studies liver visualization has been attributed to metabolism of hormones and thyroglobulin synthesized by differentiated thyroid cancer cells." (PMID 31049077, 2019). "Endogenous thyroid-stimulating hormone-stimulated thyroglobulin collected after total thyroidectomy is a useful predictor of better prognosis in patients with differentiated thyroid carcinomas in general, but studies with microcarcinomas are scarce." (PMID 29157630, 2019). "Thyroid cancer recurrence is evaluated using serum thyroglobulin (Tg) and imaging studies including I-131 WBS and neck ultrasound." (PMID 30627457, 2018). "Rest of the reduction was attributed to fact of categorizing the test under a specific profile for the study of differentiated thyroid cancer with thyroglobulin." (PMID 30429677, 2018). "In our patient, another possibility, thyroid cancer, was excluded by the finding of negativity for both thyroglobulin and TTF1, the former being highly specific to follicular neoplasms with the exception of poorly differentiated and anaplastic types." (PMID 29960592, 2018). "The carcinogenicity of BRAFV600E in the thyroid glands was first demonstrated in vivo in Tg-BrafV600E transgenic mice expressing BRAFV600E under control of thyroid-specific thyroglobulin (Tg) promoter; these mice developed thyroid cancers very early in life." (PMID 30086162, 2018). "Thyroglobulin is a critical parameter in predicting therapeutic response to 131I ablation and in monitoring recurrence or metastasis of thyroid carcinoma." (PMID 30619772, 2018). "Thyroglobulin is a glycoprotein, synthesized in thyroid cells or well-differentiated thyroid carcinoma cells." (PMID 30619772, 2018). "Curcumin increased expression of thyroid-specific genes, such as NIS and thyroglobulin in thyroid cancer cell lines." (PMID 29085335, 2017). "In patients who did not receive RAI therapy, neck ultrasound coupled with the trend in thyroglobulin values over time has the most value in identifying recurrent thyroid cancer." (PMID 26886955, 2016). "Thyroglobulin (Tg) is an important modality for monitoring patients with thyroid cancers, especially after thyroidectomy followed by radioiodine (RAI)." (PMID 27034856, 2016). "Many studies have reported that BRAFV600E mutation reduces the expression of thyroid iodine-handling genes (sodium iodide symporter, thyroid-stimulating hormone receptor, thyroglobulin, and thyroperoxidase) in thyroid cancer." (PMID 26857243, 2016). "For instance, Rab5 and Rab7 have been reported to accelerate thyroglobulin endocytosis and subsequent transfer into the proteolytic compartment, and therefore act as tandem regulators of thyroid hormone production in thyroid cancer." (PMID 26110570, 2015). "Although the patient had a recurrent history of multinodular goiter, high thyroglobulin level and bilateral pulmonary goiter nodules, she ultimately accepted the management of metastasizing thyroid carcinoma." (PMID 26047938, 2015). "The serum marker Thyroglobulin (Tg) plays a pivotal role in the follow-up of differentiated thyroid cancer." (PMID 24906384, 2014). "In some cases, determination of thyroglobulin levels in the washout fluid of neck lymph nodes is of particular note as thyroglobulin is a sensitive and specific marker of well-differentiated thyroid cancers." (PMID 23165002, 2013).